CD4 (CD4 molecule)
Diseases named in the same sentence as CD4 in open-access papers (continued):
Sharing a sentence is not in itself a finding about the gene and the disease.
melanoma (continued). "mRNA vaccines are unique in their ability to activate multiple arms of the immune system (B cells, CD4+ and CD8+ T cells), and preliminary (not yet published) data with the Moderna melanoma neoantigen vaccine appears promising in the Phase 2 study." (PMID 37063845, 2023). "Thus, the increased frequencies of IFNγ-producing Tregs or CD4 Teffs, and granzyme Bhigh CD8 Teffs in TILs by anti-PD-1 and anti-CD80 treatment may all have contributed to the melanoma regression, suggesting a potential combination therapy for melanoma with PD-1 and CD80 Abs." (PMID 35449134, 2022). "When topical Imiquimod was combined with intradermal administration of the NY-ESO-1 TSA to treat patients with malignant melanoma, NY-ESO-1 CD4+, but not CD8+, T cell responses were detected." (PMID 35651800, 2022). "First, the inhibition of the dipeptidylpeptidase DPP4 dampens the CXCL10 degradation, thus improving the CD4 and CD8 T-cell recruitment and limiting the melanoma and colon tumor growth in the presence or not of anti-PD-1 and/or anti-CTLA-4." (PMID 36429101, 2022). "(b–g) TCRβ repertoire analysis for CD8+ (b, d, f) and CD4+ (c, e, g) double-positive (DP) and non-DP TIL subsets sorted from metastatic lymph nodes of eight melanoma patients." (PMID 35377314, 2022). "A contributing factor to the lack of optimal CD4+ T cell activation is the absence or low levels of the co-stimulatory molecules CD80 and CD86 on melanoma cells." (PMID 35162988, 2022). "Characterization of CD4+ T cell residency was based on CD69+ expression, finding that the majority of CD4+ T cells in primary melanoma are not tumor-resident (CD69+ = 26.5%, CD69- = 72.27%, p = 0.0022)." (PMID 36003398, 2022). "The immune infiltrate of regressed melanoma has been proven to have lower counts of CD25+/CD4+, FOXP3+/CD4+, and PD1+/CD4+ lymphocytes compared to the non-regressed ones." (PMID 33925387, 2021). "Of note, another studied found that adoptively transferred OVA-specific CD4+ Th2 cells, but not Th1 cells, inhibit the growth of lung metastases produced by an OVA-transfected B16 melanoma (B16-OVA)." (PMID 34135885, 2021). "Importantly, we identified significant correlations between the expression of MCMs and the infiltration of immune cells (B cells, CD4+ T cells, CD8+ T cells, macrophages, neutrophils, and dendritic cells), which may provide new clues for immunotherapeutic targets and prognostic markers for melanoma." (PMID 34490114, 2021). "For the 1 (of 12) mouse that failed to reject brain implanted B78 melanoma cells, we observed an increased number of CD8+ and CD4+ T-cells compared with brain tumors in naïve mice." (PMID 32690669, 2020). "In metastatic melanoma, PD‐L1+ expression on both melanoma cells and macrophages was shown to correlate with high levels of intra‐tumoral CD8+ cells but not with intra‐tumoral CD4+ Tregs." (PMID 33072322, 2020). "On the opposite, melanoma patients' PBL neither proliferated nor differentiated into NK cells, expressing essentially CD3 and CD4 molecules." (PMID 32231660, 2020). "Unlike CD4+ and CD8+ T cells observed in melanoma patients, T cells observed in breast tumors showed differential expression of the CD27 cell surface marker, where only half of the CD28+ cells were also positive for cell-surface CD27." (PMID 31417550, 2019). "Splenic CD4+ and CD8+ T cells (> 95% purified) were co-cultured with bone marrow-derived melanoma antigen-pulsed DCs, in the presence or absence of MSCs (naïve, untreated) or TC-MSCs for 72 h with or without NLGP." (PMID 31547863, 2019). "In a related study, exosomes that were derived from CD4+25+ and CD8+25+ Tregs repressed CD8+ T cell mediated immunity against B16 melanoma cells both in vitro and in vivo, indicating a negative function for Treg exosomes in antitumor immune responses." (PMID 31615107, 2019). "We found that both CD4+ and CD8+ T cells, but not control B cells, proliferated in response to the scDb in the presence of TRAIL-R2+ melanoma cells." (PMID 31708930, 2019).
melanoma (continued). "Naïve CD4+ T cells were polarized to secrete IL-17, and infused into mice with B16F10 melanoma after a nonmyeloablative total body irradiation (5 Gy) preparative regimen." (PMID 30400835, 2018). "Consistent with this, G-1 pretreatment of human melanoma cells also inhibited subsequent tumor growth in SCID mice, indicating that G-1 has anti-tumor activity that is independent of CD4 +or CD8+ T cells." (PMID 29336307, 2018). "We detected type I CD4+ and CD8+ antigen-specific T cell immunity against shared melanoma antigens at baseline in the absence of prior vaccination We examined melanocytic lineage antigens (MART-1, gp-100) as well as the cancer testis antigen NY-ESO-1." (PMID 29973204, 2018). "Importantly, when using PBMC from patients with melanoma in allogeneic coculture assays, we could observe a similar tendency of the PD-1/TIM-3 and PD-1/BTLA combinations to enhance proliferation, with TIM-3 being particularly effective in both CD4 and CD8 T cells." (PMID 28588576, 2017). "Although to a markedly lower extend compared to tetramer+ CD8+ T cells, tetramer+ CD4+ T cells were also capable of mediating specific cytotoxicity and producing IFN-γ when cocultured with Mel 624, but not Mel 888, melanoma cells." (PMID 26824989, 2016). "CD4+ T-cell infiltration, but not CD8+ T-cell infiltration, has been shown to correlate with the spontaneous regression of primary melanoma, BCC, keratoacanthoma, and a mouse model of UV-induced SCC." (PMID 25340823, 2014). "We observed a robust CD4+ proliferative response against KLH in all patients, comparable to previous studies in colorectal cancer and melanoma patients who were vaccinated with the same vaccine without chemotherapy." (PMID 20924373, 2010). "CD4+ T cells specific for this epitope were detected among PBMCs and in the TILN from melanoma patients but not in healthy control individuals." (PMID 20981248, 2010). "Double immunohistochemistry for the melanoma protein MART1 and CD8 demonstrated that the melanoma cells (red staining) were surrounded by infiltrating CD8+ T cells (brown staining) but not CD4+ T cells (data not shown)." (PMID 18334033, 2008). "CD4+ clones DB5 and MC5 killed the recipient melanoma cell line WMPG specifically and not recipient PHA blasts or the LG2-EBV feeder cell line." (PMID 16819544, 2006). "Methionine supplementation allows its preferential uptake by CD4+ T cells rather than by tumor cells, in turn promoting AMPK activation of CD4+ T cells and restricting PD-1 expression to strengthen anti-tumor immunity and restrict tumor growth in B16 melanoma." (PMID 41557725, 2026). "The frequency of IL-2+ cells within CD3+, CD4+, and CD8+ T cell populations significantly decreased after coincubation with human melanoma A375 cells regardless of IFN-γ pre-exposure (p < 0.05), while no significant change was seen after coincubation with Hermes 1 cells." (PMID 40574005, 2025). "In mice bearing melanomas without functional MLKL-mediated necroptosis signaling, ICI immunotherapy failed to boost activation and cytolytic function of CD8+ tumor-infiltrating T cells and had reduced effects on CD4+ T cell activation." (PMID 40345706, 2025). "Moreover, it has been shown that combinatorial immunotherapy using LB-100, a PP2A inhibitor together with PD-1 blockade further enhances CD4+ and CD8+ T cell-mediated antitumor immune responses in mouse melanoma model without inducing autoimmunity." (PMID 37234102, 2023). "The area under the curve (AUC) for PD-L1, CD4, and CD8 biomarkers was from 0.941 to 0.975, which means a very good ability of the ROC test to discriminate the presence or absence of malign tumoral melanoma cells." (PMID 36836455, 2023). "The area under the curve (AUC) for our studied biomarkers (PD-L1, CD4 TILs, and CD8 TILs) starts from 0.941 to 0.975, which means a very good ability of the ROC test to discriminate the presence or absence of malign tumoral melanoma cells." (PMID 36836455, 2023).
melanoma (continued). "Most melanoma cells do not express MHC class II molecules, the main function of which is to present processed antigens, mainly derived from foreign sources, to CD4+ T lymphocytes; they are therefore essential for the initiation of antigen-specific immune responses." (PMID 36438905, 2022). "Although there were no significant changes in the number of CD4+ and CD8+ T cells in livers of Lyve-1 KO mice bearing established melanoma metastases, tumor-free livers of Lyve-1 KO mice showed significant increased numbers of CD4+ and CD8+ T cells, Treg cells and eosinophils." (PMID 36496412, 2022). "Notably, NLRC4 can promote cytokine and chemokine release in TAMs and amplify protective IFN-γ-producing CD4+ and CD8+ T cells, thereby diminishing tumor growth in melanoma independent of inflammasome assembly." (PMID 35990696, 2022). "We show that Activin-A secretion by melanoma cells inhibits adaptive antitumor immunity irrespective of BRAF status by inhibiting CD8+ T cell infiltration indirectly and even independently of CD4 T cells, at least in part by attenuating the production of CXCL9/10 by myeloid cells." (PMID 35580932, 2022). "We performed several additional comparisons between cancer cells and matched non-cancer cells, including the leukemia cell Jurkat versus CD4+ T cell, breast cancer cell line MCF7 versus MCF10A, MDA-MB-231 versus HMEC, MCF7 versus HMEC, and melanoma cell SK-MEL-28 versus HEM." (PMID 33144558, 2020). "Activated T cells (CD4+ and CD8+) thus showed significant migration toward supernatants from a PBMC co-culture with melphalan-exposed melanoma cells, but did not migrate significantly toward supernatants obtained from co-cultures of PBMCs and melanoma cells in the absence of melphalan." (PMID 32002296, 2020). "After re-stimulation of blood lymphocytes ex vivo with melanoma Trp2 or OVA peptides, significant CD8 T-cell responses against both antigens could be detected, and the responses were not dependent on CD4 T-cell help." (PMID 31333674, 2019). "Earlier attempts at releasing the suppression of conventional CD4+ and CD8+ T cells in CRC with anti-PD-1 and anti-CTLA-4 blockade, which have shown excellent results in therapy of advanced melanoma and prostate cancer, have failed, and so far no specific immunotherapy has been registered for CRC." (PMID 30651930, 2018). "Moreover, this study highlighted that the absence of sNKG2DL in the pre-treatment serum of melanoma patients with improved OS correlated with the enrichment of few circulating T cell subsets (e.g., CD3+CD4+CD45RO+BTLA+, CD3+CD4+4-1BB+, and Th17)." (PMID 30004433, 2018). "However, when we plotted pSTAT1 staining level in association with age, we observed a significant inverse correlation in pSTAT1-expressing CD4+ T cells, CD56hi and CD56low NK cells, but not CD8+ T cells with age in melanoma patients but not healthy controls." (PMID 27153543, 2016). "Assuming that ACT of TRP-1-specific CD4+ T cells could reject established melanoma tumors in IL-15−/−RAG−/− mice, we could use this model to dissect the activity of NK cells on adoptively transferred CD4+ T cells without also activating Fc receptors." (PMID 26405570, 2015). "Therefore, despite its ability to preserve CD4 T cell help, anti-CD25 treatment did not completely deplete Treg cells, nor induce CD8 T cell responses to melanoma." (PMID 22046294, 2011). "Also, HLA class II positive melanoma directly participates in and stimulates TCR expressed by CD4+ Treg, while in the absence of HLA class II tumor expression, TILs can be stimulated indirectly by stimulating tumor antigens through Antigen-presenting cells (APCs)." (PMID 36646683, 2023). "To verify whether there is concurrent enrichment with convergent TCR clusters, we performed fluorescence-activated cell sorting (FACS) of CD39+PD-1+ (double-positive [DP]) and non-DP CD4+ and CD8+ T cells from TILs freshly isolated from lymph node metastases from eight melanoma patients." (PMID 35377314, 2022).
melanoma (continued). "Three weeks after inoculation with B16.SIY melanoma cells, the R microbiota-reconstituted mice exhibited a significant increase in SIY-specific CD8+ T cells (thereby augmenting priming of tumor antigen-specific CD8+ T cells), but no change was observed in FoxP3+CD4+ regulatory T cells." (PMID 33783613, 2021). "Moreover, CD4+ Teff cells commonly do not capture melanoma antigens from cells lacking MHC class-II molecules, although a number of studies proved that the majority of melanoma cells are restored in class-II expression by high levels of IFN-γ." (PMID 29285320, 2017). "Additionally, we observed in the melanoma model that CBs with or without ISAV fusion protein reduce tumor growth in prophylactic treatment; however, only ISAV expressing CBs showed an increase CD4 and CD8 cells in spleen." (PMID 29062313, 2017). "After successfully stimulating an antitumor immune response against the GILT expressing melanoma, the patient's melanoma cells, not expressing GILT, could be recognized by both immune effector cells, CTLs and NK T cells, and immune regulating CD4+ T cells; further improving tumor regression." (PMID 20016802, 2009). "To investigate whether the superior protection of MCJ KO hosts against the B16-OVA melanoma could be due to the absence of MCJ in T cells, we used T cell conditional MCJ KO mice (hereinafter referred to as T-cMCJ KO mice) generated by crossing MCJfl/fl mice with CD4-Cre mice." (PMID 38789421, 2024).
lymphopenia (1,152 papers, 1998 to 2026). Reduction in the number of lymphocytes. "Lymphopenia (<1200 cells/μL) was observed in 84%, with 61.1% showing CD4+ T cell deficiency, 32.2% NK cell deficiency, 46% CD8+ T cell reduction, and 26.6% decreased plasma cells." (PMID 41717445, 2026). "Immune deficiencies involving cellular-mediated immune responses and CD4 lymphopenia have been documented to be associated with T. marneffei infection, thus increasing susceptibility to the infection." (PMID 39911395, 2025). "Normal T- and B-cell proliferation has been reported in a patient with the IL2RG variant p.(Asp134Val), who also suffers from CD4+ lymphopenia and antibody deficiency." (PMID 40170851, 2025). "Research demonstrates an association between disease severity and T cellular lymphopenia, particularly in CD4+ and CD8+ T cells, alongside elevated exhaustion markers (PD-1, TIM-3)." (PMID 40806391, 2025). "To identify the underlying mechanism of lymphopenia and classify CD4 T cell subsets in an unbiased manner, we clustered cells based on their transcriptomic profiles and assessed the robustness of the clusters’ identity." (PMID 40096073, 2025). "Despite its association with peripheral lymphopenia, and specifically CD4 + lymphopenia, the original landmark clinical trials demonstrated similar overall incidences of infection between participants treated with fingolimod, and control groups." (PMID 40548133, 2025). "Age, CD4 lymphopenia, and thrombocytopenia were risk factors for mortality, which occurred in 20% of cases." (PMID 40748951, 2025). "Regarding lymphocyte subsets, CD4+ lymphopenia was observed in 34.5% of patients with BRAF mutations, whereas only 9.1% of MAP2K1-mutated individuals exhibited this finding." (PMID 40692796, 2025). "Prolonged oral corticosteroid use, even at moderate doses, can induce secondary immunodeficiency characterized by significant CD4+ lymphopenia and decreased IgG levels, thereby increasing susceptibility to opportunistic and bacterial infections." (PMID 40564746, 2025). "Corticosteroids are well known to cause multiple immune defects, most notably CD4+ T-cell lymphopenia." (PMID 41583153, 2025). "Clinically, our findings emphasize the need to consider MHC II deficiency in infants with recurrent infections, profound CD4 lymphopenia, and reduced HLA-DR expression, particularly in consanguineous families or those with affected siblings." (PMID 41376631, 2025). "This complication probably occurs due to immune dysregulation in the setting of profound CD4+ lymphopenia caused by 2CDA." (PMID 41031578, 2025). "CD4 + T cells recover via thymopoiesis and develop a new T cell receptor repertoire and therefore a profound CD4 + T cell lymphopenia has been assumed as a cause of action." (PMID 38509633, 2024). "In this study, we demonstrate that conditional ablation of Ripk1 in conventional T cells (Ripk1ΔCD4) causes peripheral T cell lymphopenia, as witnessed by a profound loss of naive CD4+, naive CD8+, and FoxP3+ regulatory T cells." (PMID 38734851, 2024). "HIV is another infectious disease that is associated with CD4+ lymphopenia leading to significant immunodeficiency, where CD4+ lymphocytes are either directly infected or become unfunctional." (PMID 38965547, 2024). "In conclusion, our study provides novel insights into TRAP1 mutations associated with CD4+ lymphocytopenia and PjP susceptibility." (PMID 39224595, 2024). "SARS-CoV-2 infection also causes pronounced lymphopenia and the apoptosis of CD4+ and CD8+ T cells, limiting antigen presentation and B-cells, which are critical for antibody production." (PMID 38786660, 2024). "The disease is characterized by infections, atopy, and multiorgan defects, often accompanied by the loss of naive CD4+ T cells and lymphopenia." (PMID 39776909, 2024).